CD83 (CD83 molecule)
Diseases named in the same sentence as CD83 in open-access papers (continued):
Sharing a sentence is not in itself a finding about the gene and the disease.
Allergy (4 papers, 2019 to 2025). An allergy is an immune response or reaction to substances that are usually not harmful. "Probiotic supplementation with Escherichia coli EcO83 in newborns of allergic mothers reduced allergy incidence at 10 years, likely through immune modulation (increased IL-10, CD83 expression)." (PMID 41010534, 2025). "Next, the MFI of CD83 was evaluated in children divided into two groups based only on their allergy status." (PMID 36703968, 2022). "CD83+ dendritic cells have been shown to be higher in nasal mucosa biopsies in allergy." (PMID 31690037, 2019). "When the MFI of CD83 was compared in children sorted according to their allergy status, no change in the MFI of CD83 was observed on mDCs of allergic children in comparison with non-allergic ones." (PMID 36703968, 2022). "Surprisingly, neither EcO83 stimulation nor maternal allergy status had an effect on the cell surface presence of CD83 on pDCs." (PMID 36703968, 2022). "When the proportion of CD83+ mDCs was compared in healthy and allergic children regardless of their maternal allergy status and eventual EcO83 supplementation, an elevated presence of CD83 was measured on mDCs of allergic children in comparison with that in non-allergic ones (p = 0.0067)." (PMID 36703968, 2022). "After subdivision of children according to their allergy status, non-significant values of the MFI of CD83 on mDCs of A N AM and A S AM were ascertained." (PMID 36703968, 2022).
Alzheimer disease (4 papers, 2020 to 2025). A progressive, neurodegenerative disease characterized by loss of function and death of nerve cells in several areas of the brain leading to loss of cognitive function such as memory and language. "In Alzheimer’s disease (AD), a specific CD83+ microglial subtype has been identified in 47% of patients, and is associated with protective immune responses, including antigen presentation and amyloid clearance." (PMID 40777014, 2025).
Arthritis (4 papers, 2019 to 2022). Inflammation of a joint. "In conclusion, DCR-5 conferred protection from arthritis by targeting CD83, resulting in selective depletion of mature cDC and subsequent increases in DCreg and Treg." (PMID 35222372, 2022). "In this study, it was found that the frequency of CD83+ cells was higher in BD patients with arthritis than in healthy controls." (PMID 34531862, 2021).
breast tumors (4 papers, 2003 to 2013). "CD83 expression in DCs within primary breast tumors was shown to correlate directly with clinical outcome." (PMID 24088396, 2013). "We observed that the percentage of mature CD83+ DCs is higher in patients with invasive breast cancer compared with subjects of all other groups (in situ carcinoma, benign breast neoplasms and healthy controls)." (PMID 14562018, 2003). "Since there have been no previous evaluations of this antigen in breast tumors, we can propose that CD83 expression is an indicator of the prognosis of lesions and/or is indicative of the future risk of malignant neoplasm." (PMID 22249796, 2011). "The maturity and location of DC within breast tumours may not be uniform, such that more mature DCs, expressing differentiation/activation markers such as CD83, have been noted to be located peritumourally around the tumour mass, rather than infiltrating within it." (PMID 12888826, 2003).
cervical carcinoma (4 papers, 2017 to 2024). A carcinoma arising from either the exocervical squamous epithelium or the endocervical glandular epithelium. "As the underlying mechanism, it was shown that cervical cancer cells actively interfere with NF-κB activation in CD83+ phenotypically mature dendritic cells." (PMID 28895886, 2017). "For example, somatic mutations of CD83 with unknown significance have been reported in DLBCL and polymorphisms of CD83 were correlated with prognosis of cervical cancer." (PMID 31231400, 2019). "The CD83+ cell distributions in cervicitis, cervical dysplasia, and cervical carcinoma were then analyzed." (PMID 39529763, 2024). "In cervical cancer patients, mature CD83+ dendritic cells are present in the tumor stroma." (PMID 28895886, 2017).
endometriosis (4 papers, 2013 to 2022). The growth of functional endometrial tissue in anatomic sites outside the uterine body. "A case-control study was performed to evaluate the diagnostic potential of serum CD90 and CD83 levels in endometriosis patients (cases validated by surgical and histological examination) compared to healthy controls." (PMID 35769819, 2022). "The density of CD1a+ (immature) DCs is increased during the proliferative phase in the basal layer of the endometrium, and the density of CD83+ (mature) DCs is decreased across all stages of the menstrual cycle in women with endometriosis." (PMID 33807420, 2021). "This led us to investigate two soluble molecules, CD83 and CD90/Thy-1, which have not yet been tested in connection with endometriosis." (PMID 35769819, 2022).
experimental autoimmune encephalomyelitis (4 papers, 2013 to 2023). An autoimmune demyelinating disease of the central nervous system that is produced experimentally in animals by the injection of homogenized brain or spinal cord in Freund's adjuvant. "Using single-cell RNA-sequencing, we reveal that conditional deletion of CD83 results in an over-activated state during neuroinflammation in the experimental autoimmune encephalomyelitis model." (PMID 37528070, 2023). "Treatment with soluble CD83 can inhibit pathological symptoms of experimental autoimmune encephalomyelitis (EAE) and experimental autoimmune uveitis (EAU)." (PMID 31582900, 2019).
Granuloma (4 papers, 2013 to 2020). A compact, organized collection of mature mononuclear phagocytes, which may be but is not necessarily accompanied by accessory features such as necrosis. "In the liver, CD83+ mononuclear cells were found in the inflammatory infiltrates of portal spaces and in the periphery of granulomas." (PMID 32131896, 2020). "In five cases, CD83 was occasionally expressed by granuloma cells." (PMID 23464965, 2013).
HIV-1 infection (4 papers, 2011 to 2024). The type species of lentivirus and the etiologic agent of acquired immunodeficiency syndrome (AIDS). "Upon HIV-1 infection, the basolateral detached DCs exhibit a semi-mature phenotype as evident from upregulation of activation marker CD83 and to a lesser degree CD86." (PMID 39729509, 2024). "Contrasting the downmodulation of CD83 upon HIV-1 infection, the exposure of DCs to inactivated HIV-1 virions or recombinant gp120 (HIV-1 strains Ada or IIIB)/Tat protein results in the upregulation of CD83 expression levels due to the induction of a mature phenotype." (PMID 32362900, 2020).
Hodgkins lymphoma (4 papers, 2019 to 2023). A heterogeneous group of malignant lymphoid neoplasms of B-cell origin characterized histologically by the presence of Hodgkin and Reed-Sternberg (HRS) cells in the vast majority of cases. "CD83 is expressed on activated immune cells including B cells and is a therapeutic target for Hodgkin lymphoma." (PMID 32685149, 2020). "Some tumor cells have high expression of CD83 on the cell surface, such as Hodgkin lymphomas (HLs), diffuse large B‐cell lymphoma, adult acute lymphoblastic leukaemias, gastric extra‐nodal marginal zone lymphomas and lung cancer cells." (PMID 32685149, 2020). "The first malignancy to be reported exhibiting surface CD83 expression was Hodgkin lymphoma (HL)." (PMID 31231400, 2019). "Interestingly, although CD83 expression in Mino cells is not as high as that on the classical Hodgkin lymphoma cells, KM‐H2, they have a similar sensitivity to the anti‐CD83 ADC." (PMID 32685149, 2020).
multiple sclerosis (4 papers, 2019 to 2025). A progressive autoimmune disorder affecting the central nervous system resulting in demyelination. "On the other hand, the OL_7 subcluster expressed markers of immune cells such as C3, CD74, and CD83, therefore sharing a common transcription profile with the ImOLG population described in multiple sclerosis." (PMID 40293058, 2025). "However, both vitDC and EPDC reduced expression of HLA-DR, CD86, and CD83 in comparison to mDC, both in healthy and multiple sclerosis individuals." (PMID 30792716, 2019). "For instance, in a mouse model of multiple sclerosis, TGF-β and GM-CSF secreted by the BBB have been shown to induce the differentiation of CD14+ BBB-bound monocytes towards CD83+CD209+ DCs." (PMID 36495563, 2023).
rheumatoid arthritis (4 papers, 2014 to 2025). A chronic, systemic autoimmune disorder characterized by inflammation in the synovial membranes and articular surfaces. "In addition to the transmembrane form of CD83, an alternative isoform of soluble CD83 (sCD83), which results from the alternative splicing of full-length CD83, had been found in the serum of healthy adults and patients with leukemia, malignant tumors, and rheumatoid arthritis." (PMID 24586642, 2014).
colorectal cancer (3 papers, 2016 to 2020). A primary or metastatic malignant neoplasm that affects the colon or rectum. "The aim of this study was a detailed analysis of the presence of mature dendritic cells (CD83 positive) in colorectal cancer in correlation with selected clinicopathological parameters." (PMID 26839537, 2016). "In addition, it has been shown that DCs expressing the maturation marker CD83 are present in colorectal cancer." (PMID 30984181, 2019). "What is more, it was found that patients with a reduced number of CD83 positive cells in the front of the cancerous tumor or in the metastases of the colorectal cancer have worse survival rates in comparison to patients with a higher infiltration of mature dendritic cells." (PMID 26839537, 2016).
diffuse large B-cell lymphoma (3 papers, 2016 to 2025). "Since then, other tumors have been shown to express CD83, including diffuse large B-cell lymphomas (DLBCL), small cell lung cancer and other lung adenocarcinomas and gastric mucosa-associated lymphoid tissue lymphomas." (PMID 31231400, 2019).
heart failure (3 papers, 2023 to 2025). Inability of the heart to pump blood at an adequate rate to meet tissue metabolic requirements. "Heart failure comorbid with depression may be associated with five hub genes, including Stat4, Cd83, Cx3cr1, Col1a2, and Sh2d1b." (PMID 39295096, 2024). "Transcript levels of several established biomarkers, including Spp1, Sfrp1, Sfrp2, Tnc, Vim, Mmp9, and Tnfrsf1a, and several inflammatory markers that are known to be activated in heart failure, such as Cd44, Cd83, Ccl7, Irf7, and Nr4a2, were upregulated in the Myh6-McmTamDspfl/fl cardiomyocytes." (PMID 40608429, 2025).
leukaemia (3 papers, 2014 to 2022). "CD83 expression has been reported in some lymphomas and leukaemias." (PMID 32685149, 2020). "For instance, it has been reported that THP-1 cells and the CD34 + (KG-1) leukaemia cell line incubated with varying concentrations of rhGM-CSF and rhIL-4 for 5 days showed upregulated levels of CD11c, CD80 and CD86 and of the cell-surface receptors CD40, CD209 (DC-SIGN) but failed to express CD83." (PMID 34800147, 2022).
lymph node metastasis (3 papers, 2020 to 2023). "In agreement with this, patients with a significantly higher number of mature CD83+ cDCs at the invasive margin had a lower incidence of lymph-node metastasis and overall better outcomes in comparison to patients with reduced levels of CD83+ cDCs." (PMID 36980187, 2023). "Additionally, among patients with lymph node metastasis, the survival rate of those with larger numbers of CD83+ DCs intratumourally was significantly higher than that of patients with fewer CD83+ DCs." (PMID 33919875, 2021).
Obesity (3 papers, 2022 to 2023). Accumulation of substantial excess body fat. "The CD83 gene is known to contribute to T lymphocyte proliferation, and in humans, it has been shown that the T cells are actively regulated in the adipose tissue and contribute to obesity-induced inflammation." (PMID 37407918, 2023). "CD83 plays a critical role in triggering T cell responses, and its decreased expression leads to a weakened host antiviral immune response and increased severity of viral infections in patients with obesity." (PMID 36466818, 2022). "Our results demonstrated that CD83 is downregulated in lean and post-RYGB (starting at 1-year and maintained up to 5-years) compared to obesity." (PMID 36432612, 2022).
osteosarcoma (3 papers, 2014 to 2024). A usually aggressive malignant bone-forming mesenchymal neoplasm, predominantly affecting adolescents and young adults. "We identified three genes located in focal gains and overexpressed in a significant fraction of both osteosarcoma sets: CD83 (6p23), RTN1 (14q23.1), and GPR177 (WLS/EVI) (1p31.3)." (PMID 25551557, 2014). "The elevated expression of CD83, CCR7, and LAMP3 in mDCs was consistent with research on osteosarcoma." (PMID 39256364, 2024).
rectal cancer (3 papers, 2019 to 2021). A primary or metastatic malignant neoplasm that affects the rectum. "CD83 was significantly higher on DCs exposed to the mock-irradiated rectal cancer secretome compared to the mock-irradiated normal rectal secretome." (PMID 33540635, 2021). "In 13 post-nRCT rectal cancer tissues, ≥30% of pDCs expressing CD83 were present, providing evidence that these tissues can contain a marked proportion of mature pDCs." (PMID 30984181, 2019). "CD83+ pDCs were detectable in all post-nRCT rectal cancer tissues, but only in 11 out of 18 tumor tissues before nRCT at varying percentages." (PMID 30984181, 2019). "Moreover, TCM from mock-irradiated rectal cancer tissue enhanced expression of CD83 to a greater extent than NCM from mock-irradiated normal rectal tissue (p = 0.02)." (PMID 33540635, 2021). "To investigate whether nRCT influences the maturation status of rectal cancer-infiltrating pDCs, we analyzed the proportion of pDCs expressing the maturation marker CD83 in matched pre-nRCT and post-nRCT tumor samples of 18 patients." (PMID 30984181, 2019). "Furthermore, nRCT significantly increased the percentage of mature CD83+ pDCs in rectal cancer tissues." (PMID 30984181, 2019). "The percentage of CD83+ pDCs was significantly higher in post-nRCT tumor tissues (36.7 ± 18.9% CD83+ pDCs) in comparison to pre-nRCT tumor specimens (3.2 ± 4.2% CD83+ pDCs), indicating that nRCT can profoundly enhance the proportion of mature pDCs in rectal cancer tissues." (PMID 30984181, 2019). "Together with our finding that nRCT also enhances the percentage of CD83+ pDCs, these results reveal that nRCT promotes the maturation and IFN-α production of rectal cancer-infiltrating pDCs." (PMID 30984181, 2019). "There was a positive correlation between CD83 and SAA in the mock-irradiated rectal cancer TME." (PMID 33540635, 2021). "Moreover, we demonstrated for the first time that nRCT results in an accumulation of pDCs as well as an increased proportion of CD83- and IFN-α-expressing pDCs in rectal cancer." (PMID 30984181, 2019).
sarcoma (3 papers, 2020 to 2024). A usually aggressive malignant neoplasm of the soft tissue or bone. "These markers, including ICAM-1, MHC-I and CD83 were variably induced by TNF in the pediatric sarcoma cell lines tested here." (PMID 39723214, 2024). "Applying flow cytometry, immunoblotting, tumor killing and ELISpot assays, we identified TNF and IL-1β to be the strongest inducers of MHC-I, and partly ICAM-1 and CD83 on the majority of pediatric sarcoma cell lines tested." (PMID 39723214, 2024). "Both CD83 and CCR7 upregulation was significant also when compared to DCs loaded with untreated sarcoma cells." (PMID 33717062, 2021). "We observed that TNF and IL-1β upregulated MHC class I, ICAM-1 as well as CD83 and PD-L1 on the surface of pediatric sarcoma cell lines, while IL-4, GM-CSF, IL-6 and PGE2 failed to induce respective effects." (PMID 39723214, 2024). "In our PDL1-negative sarcoma cases, there is little relationship between activation and PDL1 expression in macrophages; of the 24 PDL1+ phenogroups, only seven express HLA-DR and eight CD83." (PMID 31959856, 2020). "We assessed a panel of pediatric sarcoma cell lines, including OS (SJSA-1, U2OS), RMS (RD, RH30) and EwS (A673, TC32, TC71 and SKNMC) for their basal expression of the immunogenic surface markers CD86, CD83, PD-L1, ICAM-1, MHC-I and MHC-II in comparison to healthy donor-derived PBMCs." (PMID 39723214, 2024). "Therefore, TNF is capable of upregulating ICAM-1, MHC-I and, to a lesser extent, CD83 and PD-L1 on multiple pediatric sarcoma cell lines without promoting tumor growth in vitro, and thus was further assessed for its immunostimulatory activity." (PMID 39723214, 2024).
Sepsis (3 papers, 2017 to 2022). Sepsis is defined as life-threatening organ dysfunction caused by a dysregulated host response to infection. "IL-4&GM-CSF-differentiated MO obtained from mice surviving sepsis had significantly lower expression of CD1a and CD83, two exclusive markers for monocyte-derived immature and mature cells, respectively." (PMID 28507543, 2017). "We found profound decrease of MO→iDC in the humanized mice 28 days after sepsis, demonstrated by depressed expression of CD1a, CD83, and CD209, diminished production of IL-12p70, and depressed ability to stimulate T cells in mice after CLP as compared to SHAM or CONTR." (PMID 28507543, 2017). "We did not observe any decrease in the expression of CD83 after sepsis onset." (PMID 28715505, 2017).
uveitis (3 papers, 2018 to 2019). An inflammatory process affecting a part of or the entire uvea. "The authors went one step further and described the mechanism of action by which the soluble form of CD83 was able to protect against the uveitis in mice." (PMID 30498498, 2018). "Anti‐IL‐18R antibody might serve as a potential therapeutic agent for uveitis through its capacity to inhibit CD83+CCR7+NK cells infiltration." (PMID 30548211, 2019). "In addition, we examined whether blocking of IL‐18 receptor would alleviate the development of uveitis and affect the status of CD83+CCR7+NK cells, DCs and T cells." (PMID 30548211, 2019). "The increases in IL‐18 observed in EAU might represent an important factor which promotes CD83+CCR7+ NK cell activation, thereby participating in the development of uveitis." (PMID 30548211, 2019).
allergic rhinitis (2 papers, 2020 to 2025). Inflammation of the nasal mucous membranes caused by an IgE-mediated response to external allergens. "Interestingly, a soluble form of CD83 (sCD83) with well‐described immunomodulatory functions has been shown to induce apoptosis in Th2 cells in models of allergic rhinitis." (PMID 39955650, 2025).
endometrial cancer (2 papers, 2023). Primary or metastatic malignant neoplasm involving the endometrium (mucous membrane that lines the endometrial cavity). "Resected tumor samples from patients with ovarian, cervical, and endometrial cancer were analyzed for CD83 expression." (PMID 36906640, 2023). "We hypothesized that the broader array of antibodies used (anti-CD83, -DC-LAMP, -CD1a, -CD1c, -CD123, and -DC-SIGN) would clarify the correlation between DCs’ infiltrates and the clinicopathological features of endometrial cancers." (PMID 36768258, 2023).
Ewing sarcoma (2 papers, 2021 to 2023). A small round cell tumor that lacks morphologic, immunohistochemical, and electron microscopic evidence of neuroectodermal differentiation. "Ewing sarcoma cDCs showed significantly lower percentages of CD83-, CD86-, and TNFSF9-expressing cells and Ewing sarcoma Mφ had significantly lower CD70-, CD80-, CD83-, and TNFSF9-expressing cells, than neuroblastoma." (PMID 37823774, 2023).
gastric carcinoma (2 papers, 2019 to 2020). A carcinoma that arises from epithelial cells of the stomach. "CD83-positive DCs were significantly lower in gastric carcinomas, showing deep infiltration." (PMID 33198173, 2020). "Dendritic cells expressing Langerin, CD1a, S100, CD83, CD86, and BDCA-2 were detected in gastric cancer tissue by immunohistochemical analysis." (PMID 33198173, 2020).